YTHDF1 (YTH N6-methyladenosine RNA binding protein F1)
Diseases named in the same sentence as YTHDF1 in open-access papers (continued):
Sharing a sentence is not in itself a finding about the gene and the disease.
bladder cancer (22 papers, 2020 to 2025). "Meanwhile, WTAP accelerates bladder cancer malignancy by targeting NRF2 through YTHDF1-m6A dependent ferroptosis regulation." (PMID 38550378, 2024). "It has also been reported that YTHDF1 promotes cell growth and progression of bladder cancer via recognition of the m6A sites and translation of ITGA6." (PMID 36650570, 2023). "In bladder cancer, YTHDF1 promotes bladder cancer growth and progression through the ITGA6-METTL3 pathway." (PMID 36733344, 2023). "For example, YTHDF1 promotes the growth and progression of bladder cancer via the ITGA6-METTL3 pathway." (PMID 34026603, 2021). "Yang et al34 showed that METTL3 and ALKBH5 regulated m6A modification of the 3′‐UTR of the oncogene CDCP1 mRNA and that YTHDF1 recognized m6A modification to promote CDCP1 translation in bladder cancer." (PMID 32808488, 2020). "METTL14, YTHDC1, and WTAP may be protective factors for bladder cancer, the higher expressions were related to the longer overall survival of patients, while IGF2BP1-3, YTHDF1, LRPPRC, ALKBH5, and FTO were risk factors for bladder cancer." (PMID 37701836, 2023). "Whether the m6A reading protein YTHDF1 is involved in the development of bladder cancer remains to be elucidated." (PMID 37108067, 2023). "In bladder cancer, YTHDF1 can also induce drug resistance in tumors through this pathway." (PMID 38202722, 2023). "Meanwhile, overexpression of the downstream target gene, RPN2, could rescue the effect of reduced METTL3/YTHDF1 expression on bladder cancer cells." (PMID 37108067, 2023). "The results showed that the reduced expression of METTL3/YTHDF1 could lead to decreased bladder cancer cell proliferation and cisplatin sensitivity." (PMID 37108067, 2023). "The aims of this study were to determine the association between METTL3/YTHDF1 and bladder cancer cell proliferation and cisplatin resistance to explore the downstream target genes of METTL3/YTHDF1 and to explore the therapeutic implications for bladder cancer patients." (PMID 37108067, 2023). "Similarly, Jin et al35 found that METTL3 and ALKBH5 regulated the m6A modification of the 3′‐UTR of the oncogene ITGA6 mRNA and that YTHDF1/3 recognized m6A modification to promote ITGA6 translation in bladder cancer." (PMID 32808488, 2020). "In bladder cancer, WTAP/YTHDF1 promotes cell viability of bladder cancer and inhibits erastin-induced ferroptosis by promoting the levels of the antioxidant factor NRF2 mRNA." (PMID 40271153, 2025). "Recent research has revealed that m6A modifications, including METTL3, YTHDF1, and FTO, play a pivotal role in promoting bladder cancer development and drug resistance 15-18." (PMID 40083693, 2025). "The expressions of IGF2BP1, IGF2BP3, YTHDF1, YTHDF2, and HNRNPC were significantly up-regulated in bladder cancer." (PMID 40083693, 2025). "It was found in humans and animal models that METTL3, FTO, IGF2BP1, IGF2BP3, YTHDF1, YTHDF 2, ELAV-like protein 1 (ELAVL1), HNRNPA2B1 were upregulated in bladder cancer cells." (PMID 37701836, 2023). "As the reader of m[superscript 6]A regulator genes, YTHDF1, YTHDF2 and HNRNPC were highly expressed in bladder cancer tissues compared with the normal tissues." (PMID 34521394, 2021). "In bladder cancer, METTL3 elevates the m6A level of CDCP1, enhancing its translation, which is modulated by YTHDF1, and the upregulation of METTL3 and CDCP1 is correlated with poor prognosis of bladder cancer." (PMID 33758623, 2021). "The combination of YTHDF1 and YTHDF3 promotes the translation of Integrin subunit alpha 6 (ITGA6) mRNA and the development of bladder cancer." (PMID 33692959, 2021). "Compared with normal tissues, the expression of CNV-increased m6A modulators of bladder cancer tissues (such as METL3 and YTHDF1) was significantly increased." (PMID 34604051, 2021). "In addition, YTHDF1 identifies the m6A site on NRF2 mRNA and enhances its mRNA stability, thereby accelerating the progression of bladder cancer malignancies." (PMID 38550378, 2024).
bladder cancer (continued). "A clinical study revealed that in bladder cancer cells, m6A is highly enriched in the ITGA6 transcripts, and increased m6A methylation of the ITGA6 mRNA 3′UTR promotes the translation of ITGA6 mRNA by binding YTHDF1." (PMID 36835655, 2023). "It has been confirmed that CDCP1 was overexpressed in bladder cancer cells, mediated by m6A methyltransferase METTL3, m6A reader YTHDF1 preferentially recognizes m6A residues on CPCP1 3′-UTR and enhances the CDCP1 translation, promotes bladder cancer tumorigenesis in vitro and in vivo." (PMID 36650570, 2023). "Studies also found that YTHDF1/YTHDF3 can preferentially identify the m6A-modified region in the 3 untranslated regions of ITGA6, promoting ITGA6 translation and enhancing the growth and metastasis of bladder cancer cells." (PMID 34604051, 2021). "In bladder cancer cells, YTHDF1 preferentially binds to the m6A mRNA of oncogene CUB domain containing protein 1 (CDCP1) to promote its translation, leading to the malignant transformation of urinary tract epithelium and occurrence of bladder cancer." (PMID 33692959, 2021).
Sepsis (19 papers, 2020 to 2025). Sepsis is defined as life-threatening organ dysfunction caused by a dysregulated host response to infection. "Upregulated YTHDF1 causes NLRP3 translation, and YTHDF1 deficiency promotes survival of sepsis mice." (PMID 38874470, 2024). "JAK2/STAT3 expression is decreased in YTHDF1 knockout macrophages and increased IL-17 production, which is associated with the migration of inflammatory cells into the brain during sepsis." (PMID 36158961, 2022). "Moreover, the Ythdf1−/− mice were more susceptible to LPS-mediated sepsis in vivo, evidenced by increased CXCL1 mRNA expression in the lung." (PMID 40092485, 2025). "In rat (Rattus norvegicus), the YTHDF1 knock-down macrophages could protect the brain injury and reduce the inflammation caused by severe sepsis via inhibition of JAK2/STAT3 expression." (PMID 37298300, 2023). "In sepsis, overexpressed YTHDF1 inhibits CLP‐induced inflammation in mice by upregulating E1 Ub protein ligase 1 to promote NLRP3 ubiquitination and inhibit caspase 1‐dependent pyroptosis, thereby alleviating sepsis." (PMID 40919129, 2025). "Complementarily, Zhang reported that in a mouse model of sepsis, YTHDF1 can inhibit pyroptosis of cells and alleviate the damage caused by sepsis by promoting the ubiquitination of NLRP3 and upregulating the WW domain-containing E3 ubiquitin ligase 1 (Wwp1)." (PMID 41341492, 2025). "Experimental studies in severe sepsis models indicate that YTHDF1 knockdown alleviates macrophage paralysis and endothelial damage." (PMID 41341492, 2025). "YTHDF1 deficiency in mice has been linked to increase the antigen-specific CD8+ T cell antitumor responses, and the susceptibility for sepsis." (PMID 40092485, 2025). "Meanwhile, YTHDF1 overexpression also reduced inflammation in lung, liver, and kidney tissues in mice with sepsis and helped restore the damaged tissue structures." (PMID 38193803, 2024). "As shown, either deletion of Ythdf1 or forced expression of FTO in macrophages caused more mortality, boosted inflammatory response, and worse heart dysfunction in animal sepsis models." (PMID 36864027, 2023). "YTHDF1 alleviated sepsis by upregulating the transcription of WWP1 to induce NLRP3 ubiquitination and inhibit caspase-1-dependent pyroptosis." (PMID 38022612, 2023). "It is known that YTHDF1 is the reader of m6A, which has been reported to participate in the regulation of sepsis development." (PMID 35508474, 2022). "Of note, the bioinformatics prediction in the current study found WW domain containing E3 ubiquitin protein ligase 1 (WWP1) to be a differential gene in sepsis which can be recognized by YTHDF1." (PMID 35508474, 2022). "YTHDF1 KD macrophages in rats improved the secretion of anti-inflammatory cytokines, highlighting the protective role of YTHDF1 KD macrophages in severe sepsis rats with ECMO." (PMID 36225914, 2022). "We thus first used RT-qPCR to detect YTHDF1 expression in clinical samples, the results of which revealed that YTHDF1 expression was remarkably low in patients with sepsis." (PMID 35508474, 2022). "It was noted that WWP1 and YTHDF1 were downregulated in clinical sepsis samples, LPS + ATP-treated RAW264.7 cells, and CLP-induced mice." (PMID 35508474, 2022). "The present study intends to investigate the regulatory network and function of the microarray-predicted YTHDF1 in caspase-1-dependent pyroptosis of sepsis." (PMID 35508474, 2022). "To further explore the effect of overexpression of YTHDF1 on sepsis in vivo, we overexpressed YTHDF1 in CLP-induced septic mice." (PMID 35508474, 2022). "A recent study has revealed that YTHDF1 may have an alleviatory effect on sepsis, which results from a dysfunction in the host's response to infection." (PMID 39342406, 2024).
Sepsis (continued). "The expression of E3 Ub ligase WW domain-containing protein 1 (WWP1) and YTH domain family protein 1 (YTHDF1) was found to be downregulated in the serum of both LPS- and ATP-induced mouse macrophage models and in cecum ligation- and puncture-induced sepsis mouse models." (PMID 38193803, 2024). "WWP1 is a differentially expressed gene in sepsis recognized by YTH domain-containing family protein 1 (YTHDF1), an RNA-binding protein specialized in recognizing m6A, a dynamic mRNA modification that plays a pivotal role in governing protein expression across various post-transcriptional stages." (PMID 38129384, 2023). "WWP1 might also contribute to YTHDF1-mediated alleviation of sepsis by promoting NLRP3 ubiquitination." (PMID 38129384, 2023). "In the first place, the present study revealed that WWP1 and YTHDF1 were downregulated in sepsis." (PMID 35508474, 2022). "It has been reported that YTHDF1 can promote the translation of target transcripts, indicating that YTHDF1 may alleviate sepsis by promoting WWP1 expression." (PMID 35508474, 2022). "This study clarified the regulatory role of YTHDF1 in sepsis with the involvement of WWP1/NLRP3/caspase-1 axis and found that YTHDF1 could upregulate WWP1 to enhance NLRP3 ubiquitination and restrict caspase-1-dependent pyroptosis in sepsis." (PMID 35508474, 2022). "Interestingly, in the current study, it was found through rmbase-based analysis in combination with RT-qPCR and Western blot assay that YTHDF1 could promote the expression of WWP1 in sepsis." (PMID 35508474, 2022). "This regulatory cascade mediated by YTHDF1 and WWP1 exerts inhibitory effects on inflammation and immune cell apoptosis, thereby contributing to the alleviation of sepsis symptoms." (PMID 39342406, 2024). "YTH N6-Methyladenosine RNA Binding Protein 1 (YTHDF1), m6A reader protein, induced NLRP3 ubiquitination and inhibited caspase-1-dependent pyroptosis to alleviate sepsis." (PMID 38022612, 2023). "Meanwhile, GSE100159 dataset manifested that YTHDF1 was downregulated and IGF2BP3 was upregulated in sepsis." (PMID 35508474, 2022). "Based on the results obtained in the current study, a conclusion is reached that YTHDF1 promotes NLRP3 ubiquitination by upregulating WWP1, thereby inhibiting caspase-1-dependent pyroptosis, which contributes to attenuation of sepsis." (PMID 35508474, 2022). "In order to further investigate the effect of YTHDF1/WWP1/NLRP3/caspase-1 axis on sepsis, RAW264.7 cells were transfected with oe-NC/oe-YTHDF1, or sh-NC/sh-WWP1." (PMID 35508474, 2022). "Peripheral blood of patients with sepsis was collected to determine WWP1 and YTHDF1 expression." (PMID 35508474, 2022). "Functionally, YTHDF1 recognized and stabilized METTL3-mediated m6A-modified tripartite motif-containing (Trim59) mRNA to protect the vascular endothelium against barrier dysfunction and inflammatory responses, which inhibits the evolution of ARDS during sepsis." (PMID 38112620, 2023). "Consequently, in YTHDF1 knockdown mouse brain tissue, the proportion of normal neurons (i.e., those that do not differ from cells exposed to severe sepsis) is significantly increase compared with mice with hyperemia." (PMID 36158961, 2022).
glioblastoma (17 papers, 2020 to 2024). The most malignant astrocytic tumor (WHO grade IV). "A recent report has implicated that MSI1 regulated the expression of m6A reader YTHDF1, thus involving glioblastoma cell proliferation and migration." (PMID 37675218, 2023). "Elevated YTHDF1 was associated with poor prognosis as it is thought to promote the proliferation and migration of glioblastoma cells." (PMID 34093133, 2021). "Additionally, Musashi-1 (MSI1) is a posttranscriptional gene expression regulator associated with high oncogenicity in glioblastoma that positively regulates the expression of YTHDF1." (PMID 35625706, 2022). "We report that the ADAR1 protein level is increased by METTL3 and YTHDF1 proteins, both abundantly expressed in glioblastoma (GBM)." (PMID 33509238, 2021). "We also demonstrated that A172 and LN229 glioblastoma cells showed YTHDF1-mediated suppression of IFN responses, while HeLa and 293T cells did not." (PMID 34324489, 2021). "Moreover, the protein Musashi-1, overexpressed in glioblastoma, upregulates YTHDF1, thereby sensitizing glioblastoma cells to TMZ and inhibiting their proliferation." (PMID 38474421, 2024). "Moreover, high YTHDF1 expression significantly increases in vivo proliferation and tumor growth of glioblastoma." (PMID 36650570, 2023). "Overexpression of YTHDF1 to promote proliferation of glioblastoma cells." (PMID 34093133, 2021). "Thus, during the IFN response, the m6A-binding protein YTHDF1 enhances ADAR1 p150 expression in glioblastoma cells to facilitate A-to-I editing of self-RNA and prevent activation of dsRNA sensors." (PMID 34329302, 2021). "In glioblastoma (GBM), miR‐346 targets YTHDF1 3’‐UTR, reducing YTHDF1 mRNA levels and suppressing tumour growth." (PMID 39135292, 2024). "YTHDF1 is elevated in glioblastoma (GBM) and positively regulated by MSI1 whereas both of these proteins are related to worse prognosis in glioblastoma patients." (PMID 36650570, 2023). "YTHDF1 and YTHDF2 were found to be highly overexpressed in glioblastoma (GBM) tissues compared to normal tissues." (PMID 36999016, 2023). "It is noteworthy that YTHDF1 knockdown promotes the sensitivity of glioblastoma cells on TMZ, a major drug for glioblastoma chemotherapy." (PMID 36650570, 2023). "Here, we show that METTL3, upregulated in glioblastoma, methylates ADAR1 mRNA and increases its protein level leading to a pro-tumorigenic mechanism connecting METTL3, YTHDF1, and ADAR1." (PMID 33509238, 2021). "In glioblastoma, miR-346 targeting the 3′-UTR of YTHDF1 reduced the mRNA level of YTHDF1, inhibiting cell proliferation and tumor growth." (PMID 34108450, 2021). "We used the TCGA microarray database and compared the mRNA expression levels of five YTH domain family proteins, YTHDF1, YTHDF2, YTHDF3, YTHDC1, and YTHDC2, between 720 normal brain tissue microarray datasets and 582 glioblastoma datasets." (PMID 33317545, 2020). "We also investigated whether YTHDF1 regulates ADAR1p150 expression and IFN responses in other cell lines that include LN229 glioblastoma, HeLa, and HEK293T." (PMID 34324489, 2021). "The analysis of METLL3/METLL14 and YTHDF1 expression in these tumors is reported together with that of Ki-67, ADAR1, and CDK2 that clearly indicates ADAR1 as an important target for glioblastoma and confirmed the modulation of the ADAR1/CDK2 axis in vivo." (PMID 33509238, 2021). "Therefore, to investigate whether YTHDF1 plays a role in m6A-regulated ADAR1 expression, we silenced this gene in glioblastoma cells, demonstrating that the knockdown of this “reader” significantly decreased ADAR1 protein, without affecting its mRNA." (PMID 33509238, 2021). "Interestingly, in the cell types tested, this regulation was unique to glioblastoma cells as other cell types did not induce IFN in response to YTHDF1 depletion, suggesting that this might be a mechanism shared in human cells of glial origin." (PMID 34329302, 2021).
glioblastoma (continued). "RIP-qPCR with antibodies against YTHDF1 and YTHDF2 showed that both YTHDFs strongly bound to ADAR1p110, ADAR1p150, and ADAR2 mRNAs in A172 glioblastoma cells, whereas ADAR3 was not expressed in A172 cells." (PMID 34324489, 2021).
esophageal cancer (11 papers, 2020 to 2025). A primary or metastatic malignant neoplasm involving the esophagus. "Shown by the cBioPortal network, YTHDF1 is frequently amplified and mutated in various squamous cell carcinomas (cervical, lung, head and neck, and esophageal cancers)." (PMID 33204330, 2020). "A similar mechanism also exists in esophageal cancer, where YTHDF1 can directly interact with HCP5 (HLA Complex P5), enhancing the interaction between YTHDF1 and HK2 mRNA to promote aerobic glycolysis." (PMID 38202722, 2023). "On the other hand, a few studies have also evaluated the prognostic significance of YTHDF1 in esophageal cancer, of which the high expression of YTHDF1 is correlated with shorter overall and progression-free survival." (PMID 35884552, 2022). "From the TCGA database, we found that several m6A-associated genes, including YTHDF1, HNRNPC, ZC3H13, YTHDC2, and METTL14 were dysregulated in esophageal cancer compared to matched normal tissues." (PMID 34395102, 2021). "However, there are only a few comprehensive studies on the analysis of YTHDF1 in esophageal cancer." (PMID 35401696, 2022). "Nonetheless, further research is needed to uncover and confirm the role and mechanistic functions of YTHDF1 in PDAC and esophageal cancer." (PMID 35884552, 2022). "Importantly, we revealed that FTO operates through a regulatory network of m6A modifications that involves METTL14, YTHDF1 and AKT3 signaling, providing the first insight into the mechanism of FTO-mediated esophageal cancer progression." (PMID 38491196, 2024).